HGF (hepatocyte growth factor)
Diseases named in the same sentence as HGF in open-access papers (continued):
Sharing a sentence is not in itself a finding about the gene and the disease.
lung carcinoma (continued). "Similarly, HGF secreted by fibroblasts was implicated in lung cancer resistance to irreversible EGFR inhibitors and protected tumor cells from EGFR inhibitors in breast cancer cells bearing EGFR overexpression." (PMID 36324182, 2022). "In addition, overexpression of HGF is observed in approximately 61% of patients with EGFR-TKIs-resistant lung cancer and is known as a cause of acquired resistance." (PMID 32290402, 2020). "A body of past research shows that increased levels of HGF and/or overexpression of c-Met are associated with poor prognosis in several solid tumors, including lung cancer, as well as cancers of the head and neck, gastro-intestinal tract, breast, ovary and cervix." (PMID 30134579, 2018). "Hepatocyte growth factor (HGF) was found to be increased in the serum of patients with lung cancer and high levels of serum HGF may be associated with poor survival." (PMID 28121629, 2017). "HGF is also induced in airway epithelium by smoking, by far the biggest cause of lung cancer." (PMID 28968967, 2017). "E7050, a dual inhibitor of Met and vascular endothelial growth factor receptor two kinase, and EGFR-TKIs suppressed tumor progression in erlotinib-resistant cancer cell lines and in HGF-induced EGFR-TKI-resistant lung cancer cell lines that also have a mutation in EGFR." (PMID 28619066, 2017). "Using a transgenic mouse that overexpresses human HGF in the airways, we have previously demonstrated that the increased susceptibility of this mouse strain to lung cancer induction by a tobacco carcinogen can be reversed by a neutralizing antibody to human HGF." (PMID 21390244, 2010). "Finally, systemic HGF levels resulted to be elevated by exposure to smoke in individuals at high-risk for lung cancer, therefore strengthening the existence of a novel additional mechanism by which smoking could promote cancer progression." (PMID 29558956, 2018). "Lung fibroblasts secrete HGF, which contributes to lung cancer cell proliferation, and MET inhibitors have been shown to suppress tumor growth in mouse models." (PMID 40867310, 2025). "A three‐dimensional (3D) microfluidic device was fabricated from polydimethylsiloxane to investigate the role of hepatocyte growth factor (HGF) derived by CAFs in the chemoresistance of A549 lung cancer cells." (PMID 40740483, 2025). "Given the aberrant expression of HGF in the clinical context of lung cancer and its critical impact on specific treatments, exploring its potential applications in lung adenocarcinoma diagnosis and treatment is of great significance." (PMID 40136462, 2025). "Lactate secreted by lung cancer promotes the production of hepatocyte growth factor (HGF) by CAFs in an NF-κB-dependent manner, which activates MET-dependent signaling in cancer cells and sustains resistance to TKIs." (PMID 40565047, 2025). "MAbs targeting HGF or MET have demonstrated significant antitumour potential in non–small-cell lung cancer (NSCLC)." (PMID 40599602, 2025). "As such, we have established that TWIST1 is a critical downstream target of the HGF/MET pathway as it was required both in vitro and in vivo for HGF/MET-driven lung cancer." (PMID 38485737, 2024). "The MET receptor tyrosine kinase (RTK), and its ligand hepatocyte growth factor (HGF), have emerged as attractive targets for lung cancer treatment." (PMID 37686423, 2023). "In lung cancers, MET can be activated through various mechanisms, such as binding to HGF, overexpression, amplification, or mutation." (PMID 37686423, 2023). "GAB1 has been established to participate in HGF-induced resistance to cetuximab in lung cancer cell lines both in vitro and in vivo by promoting cell survival through AKT activation." (PMID 37627207, 2023). "IL-1β has been found to contribute to tumor progression by promoting the secretion of matrix metalloproteinases (MMPs) and hepatocyte growth factor (HGF) in lung cancer." (PMID 37772231, 2023).
lung carcinoma (continued). "Six of the included articles present data regarding the prevalence and significance of aberrant signaling through the HGF/MET pathway in lung cancer." (PMID 37568643, 2023). "Hepatocyte growth factor (HGF) increased cisplatin resistance through downregulation of AIF in lung cancer." (PMID 38259849, 2023). "Hitomi Umeguchi and his teamwork showed that HGF in plasma was significantly higher in the advanced stage of cancer and predicted poor survival as determined using 315 plasma samples from 225 lung cancer patients." (PMID 37828456, 2023). "Using a pair of MET WT and METex14 lung cancer cell lines models, we demonstrated that the HGF/MET signaling pathway plays a critical role in enhancing PD-L1 expression with higher levels of PD-L1 in METex14 cell lines compared to MET WT." (PMID 37444481, 2023). "Compared with MET, the potential of HGF as a prognostic indicator of lung cancer is significantly smaller and controversial." (PMID 35664309, 2022). "HGF/c-met signal transduction appears to have a close relation with lung cancer occurrence, invasion and metastasis." (PMID 35568918, 2022). "The MET receptor tyrosine kinase (RTK) and its ligand hepatocyte growth factor (HGF) play an important role in cancer development as well as in innate and acquired resistance to lung cancer treatment, including EGFR inhibition." (PMID 36230855, 2022). "In particular, CAF-derived HGF mediates intrinsic resistance to afatinib in lung cancer by activating the MET/PI3K/AKT and MET/MAPK/ERK signaling pathways and triggering the progression of EMT and, chemoresistance development." (PMID 36359776, 2022). "Accordingly, increased production of stromal HGF was detected in the stroma of lung cancer patients upon the emergence of resistance to EGFR TKIs, thus corroborating the clinical relevance of the reported findings." (PMID 36324182, 2022). "Growing evidence has indicated that HGF can induce c-Met activation, which promotes membrane ruffling, motility, migration and other tumor-related activities in lung cancer." (PMID 35568918, 2022). "It was shown that blocking c-Met/HGF (C-Met ligand) interaction would suppress MMP-9 activity in lung cancer." (PMID 35986321, 2022). "Immunohistochemical staining demonstrated that HGF protein in lung carcinoma tissues exhibited elevated expression as comparing with adjacent normal tissues." (PMID 35568918, 2022). "Increased levels of HGF in plasma has been shown to correlate with poorer overall survival, and patients with stage I lung cancer with high levels of expressed HGF have a poorer prognosis than patients with stage II–III lung cancer with low expression of HGF." (PMID 36359256, 2022). "As for how HGF affects the occurrence of lung cancer by regulating the cell death program, its internal mechanism is still insufficiently studied." (PMID 35664309, 2022). "In contrast to the miR-144-3p expression level, HGF showed a higher level in lung cancer tissues and cell lines." (PMID 35568918, 2022). "When compared to healthy individuals and lung cancer patients with early stage (I/II) disease, lung cancer patients with late stage (III/IV) disease had enriched HGF in their plasma sEVs." (PMID 35158999, 2022). "Curcumin was shown to inhibit epithelial–mesenchymal transition (EMT) and angiogenesis in HGF-induced lung cancer cells by regulating c-Met-dependent PI3K/Akt/mTOR signaling pathways." (PMID 34299042, 2021). "This study showed that knockdown of SIPA1 reduced the response of lung cancer cells to HGF in terms of invasion and barrier function." (PMID 33917539, 2021). "In lung cancer, hepatocyte growth factor induces gefitinib resistance via repressing miR-1-3p expression in PC-9 and HCC827 cells, whereas miR-1-3p restoration abolishes the drug resistance by inhibiting c-Met signaling." (PMID 34395415, 2021).
lung carcinoma (continued). "Elemene and HGF combined with gefitinib significantly inhibited the invasive ability of lung cancer PC-9 cells and upregulated the protein levels of p-Met and p-AKT." (PMID 34641334, 2021). "In lung cancer, non-small-cell lung cancer, liver cancer, and prostate cancer, HGF was found to induce EMT, thereby regulating tumor cell proliferation, migration, and EMT." (PMID 34408780, 2021). "The same co-amplification of MET and HGF is reported to be a relatively frequent genetic aberration of various cancer types including lung cancer or renal cancer serving as a useful target for anti-MET therapies." (PMID 34885093, 2021). "Extensive evidence has suggested that the HGF/MET signaling pathway is essential in lung cancer tumorigenesis and progression via the alteration of cell apoptosis, growth, migration and morphology." (PMID 33917539, 2021). "Hepatocyte growth factor (HGF) is a known driver of both lung cancer pathobiology as well as M2 polarization, and its signaling is antagonized by the tumor suppressor gene HAI-1 (SPINT1)." (PMID 34185790, 2021). "HGF decreased the barrier function of lung cancer cells, which was counteracted by SIPA1 knockdown with similarity to the small molecule MET targeted inhibitor, Crizotinib." (PMID 33917539, 2021). "In lung cancer tissues, HGF and PTX3 expression was downregulated and S100P expression was upregulated." (PMID 34745947, 2021). "Collectively, the HGF/c-Met axis and ncRNAs play an essential role in the formation and development of lung cancer." (PMID 32083078, 2020). "In EGFR mutant lung cancer, cMet amplification and increased tumoral HGF expression are common mechanisms of both de novo and acquired resistance to EGFR TKIs." (PMID 32545260, 2020). "HK2 has already been shown to be upregulated upon HGF stimulation in a lung cancer model and to promote the proliferation and survival of laryngeal squamous cell carcinoma." (PMID 31940827, 2020). "Once the success of this approach had been established, the HGF knockdown MRC5 cells (MRC5-HGF) were co-cultured with the lung cancer cell lines." (PMID 31963196, 2020). "A study suggested that a panel of four biomarkers composed of prolactin, CRP, NY-ESO-1, and HGF to screen for lung cancer." (PMID 31976313, 2020). "Platelet-derived EVs enhanced tumor progression and angiogenesis in a mouse lung cancer model, through the upregulation of factors associated with tumor vascularisation, such as IL-8, VEGF, and HGF (hepatocyte growth factor)." (PMID 31920664, 2019). "c-Met receptor tyrosine kinase (RTK), activated by its ligand hepatocyte growth factor (HGF), is frequently hyperactivated, amplified or mutated in many human cancers including lung cancer." (PMID 31060329, 2019). "Recent study has shown that HGF plays a vital role in respiratory diseases, such as, lung cancer, inflammation and fibrosis." (PMID 31920638, 2019). "Multiplex assays and ELISA were instrumental to study the effect of miRNAs on the secretome of both primary and immortalized lung fibroblasts from lung cancer patients and to evaluate plasmatic levels of HGF in heavy smokers." (PMID 29558956, 2018). "The results showed that cortactin expression was induced and peaked at 60–120 min after PDBu treatment, and peaked between h in the HGF-treated lung cancer cells." (PMID 29986736, 2018). "In contrast to this, overexpression of HGF is seen in a significant number of lung cancer patients with EGFR-TKIs-resistance overlapping MET amplification." (PMID 30469509, 2018). "On the other hand, overexpression of HGF was identified in 61% of lung cancer patients with resistance to EGFR-TKIs overlapping MET amplification." (PMID 29890660, 2018). "Our study for the first time indicated the new function of miR‐1‐3p and miR‐206 in overcoming HGF‐induced gefitinib resistance in EGFR mutant lung cancer cell." (PMID 29664235, 2018).
lung carcinoma (continued). "This article will provide an update on signaling through the HGF/c-Met axis, the mechanism of action of HGF/c-Met inhibitors, the lung cancer patient populations most likely to benefit, and possible mechanisms of resistance to these inhibitors." (PMID 30134579, 2018). "In this study, we reported that miR‐1‐3p and miR‐206 can overcome HGF‐induced gefitinib resistance in EGFR mutant lung cancer cells in vitro and in vivo, and the mechanisms were related to inhibit Akt/Erk pathways and meanwhile suppress HGF‐induced EMT." (PMID 29664235, 2018). "In summary, we demonstrated in vitro and in vivo that miR‐1‐3p and miR‐206 can restore HGF‐induced gefitinib resistance in EGFR activating lung cancer cells." (PMID 29664235, 2018). "Since production of HGF by lung fibroblasts regulates lung cancer cell aggressiveness, these findings have potential clinical implications." (PMID 29558956, 2018). "Knockdown of c‐Met mimicked the effects of miR‐1‐3p and miR‐206 transfections Meanwhile, c‐Met overexpression attenuated the effects of miR‐1‐3p and miR‐206 in HGF‐induced gefitinib resistance of lung cancers." (PMID 29664235, 2018). "The second mechanism of MET regulation by TGFβ1 is related to suppression of miR‐128‐3p which, in turn, directly targets MET, which is in line with Jiang and colleagues non‐small cell lung cancer, and thereby impairs HGF/MET‐mediated cell migration." (PMID 30004628, 2018). "Plasma levels of HGF can serve as a biomarker to select lung cancer patients that would benefit from drugs that counteract the biological activity of HGF." (PMID 28968967, 2017). "Here we demonstrated that HGF also drives resistance to anti-MET therapy in MET-amplified lung cancer cells." (PMID 28968967, 2017). "In this regard, the effects of the inhibition of HGF/Met signaling on lung cancer progression have been reported." (PMID 28619066, 2017). "Another important finding of the current study is that HGF production in fibroblasts was stimulated by lung cancer cells, which seemed to exploit the fibroblasts for their own growth." (PMID 28619066, 2017). "We previously provided preclinical evidence that cytotoxic drug-resistant lung cancer cells secreted HGF and accelerated its resistance by increased expression of c-MET due to gene amplification, and that c-Met inhibitors restored cytotoxic drug sensitivity." (PMID 29069748, 2017). "A recent study demonstrated that nicotine and α7 nAChRs enhance lung cancer promotion via the HGF-induced PI3K/Akt signaling pathway." (PMID 28974241, 2017). "Elevated levels of circulating HGF are associated with a mesenchymal tumor type, poor patient prognosis and resistance to EGFR inhibitors in lung cancer patients." (PMID 28968967, 2017). "We demonstrated that novel inhibitors of HGF activation overcome fibroblast-mediated resistance to MET inhibition in MET-amplified lung cancer cells." (PMID 28968967, 2017). "Based on this perspective, we investigated the interaction between lung cancer cells and lung fibroblasts within the context of the HGF/Met pathway and its impact on lung cancer progression." (PMID 28619066, 2017). "In both MDCKII cells and lung cancer cells, HGF activates HECT, UBS, and WWE domain-containing protein 1 (HUWE1), a member of the HECT3 ubiquitin ligase family." (PMID 28475121, 2017). "In summary, we have established an in vivo imaging system for brain tumor models of EGFR‐mutant lung cancers, HGF‐dependent gastric cancers, and NTRK1‐fusion‐positive colon cancers." (PMID 29125233, 2017). "We found that HGF production within lung fibroblasts was stimulated by lung cancer cells and that HGF promoted the survival of lung cancer cells." (PMID 28619066, 2017). "Collectively, our data show that fibroblasts elicit resistance to MET-targeted therapy through HGF in MET-amplified lung cancer cells." (PMID 28968967, 2017).
lung carcinoma (continued). "It was noted again that the HGF concentration in lung cancer cell-conditioned media was lower than that in regular fibroblast-conditioned media." (PMID 28619066, 2017). "To understand how HGF signals in MET-amplified lung cancer cells when MET kinase activity is inhibited, we used the Proteome Profiler Human Phospho-RTK array (R&D Systems) to investigate the phosphorylation profiles of 49 different receptor tyrosine kinases." (PMID 28968967, 2017). "Exogenous HGF increased the survival of lung cancer cells and stimulated the phosphorylation of Met, the receptor of HGF, as predicted." (PMID 28619066, 2017). "A very recent study showed that inhibition of Tankyase 2 hampers lung cancer cell invasion and migration in response to HGF, implicating that tankyase 2 mediates HGF-induced microtubule assembly in cancer cells." (PMID 28475121, 2017). "In this study, we have established in vivo imaging models for brain tumors that mimic brain metastases for EGFR‐mutant lung cancer, HGF‐dependent gastric cancer, and NTRK1‐fusion‐positive colon cancer." (PMID 29125233, 2017). "The present study suggests that the strategy of lung cancer treatment should include the regulation of either fibroblasts or some of the factors produced by fibroblasts, such as HGF." (PMID 28619066, 2017). "Surprisingly, it has recently been shown that MET-amplified lung cancer cells become dependent on HGF for survival upon pharmacologic MET inhibition." (PMID 28968967, 2017). "The current study showed that lung fibroblasts promote lung cancer cell survival, tumorigenicity and tumor progression via HGF/Met signaling." (PMID 28619066, 2017). "We have established an in vivo imaging model for brain tumors for the epidermal growth factor receptor (EGFR)‐mutant lung cancer, the HGF‐dependent gastric cancer, and for colorectal cancer harboring the NTRK1 gene fusion." (PMID 29125233, 2017). "In this study, we reported that curcumin not only inhibits HGF-induced EMT of lung cancer cells, but also suppresses angiogenesis of HUVECs, and the mechanism is related to regulation of c-Met-dependent PI3K/Akt/mTOR signaling pathways." (PMID 27525306, 2016). "Then the antiproliferative effects of curcumin on HGF-mediated growth of A549 and PC-9 lung cancer cells were detected." (PMID 27525306, 2016). "More importantly, curcumin suppresses HGF-induced phosphorylation of c-Met/Akt/mTOR in human lung cancer cells." (PMID 27525306, 2016). "Similar results was recapitulated in Simm530-treated NCI-H441 human lung cancer cells and U-87MG human glioblastoma cells, which respond well to HGF stimulation." (PMID 27191264, 2016). "HGF, a ligand of c-Met proto-oncogene, has been reported to increase tumorigenetic, vascularizing, and motogenic effects on lung cancer." (PMID 27374174, 2016). "In the current study, we demonstrated that miR-206 overexpression inhibited HGF-induced lung cancer EMT, metastasis and angiogenesis by targeting c-Met and its downstream PI3k/Akt/mTOR (mammalian target of rapamycin) pathway." (PMID 26919096, 2016). "A study revealed that HGF activated the MET-ERK pathway, inducing resistance to erlotinib in an EGFR-mutated lung cancer cell line, KHM-3S, and the sensitivity of erlotinib was restored by crizotinib." (PMID 27331411, 2016). "In this study, we found that ectopic expression of miR-206 inhibited HGF-induced EMT, leading to suppression of HGF-induced invasion and migration in lung cancer cells." (PMID 26919096, 2016). "Autocrine activation occurs when tumor cells aberrantly express both HGF and its receptor, as observed in rhabdomyosarcomas, gliomas, carcinomas of thyroid, breast and lung cancers, (iv) HGF-independent mechanisms." (PMID 27590450, 2016). "Consistent with previous reports, we found that HGF stimulated the phosphorylation of c-Met followed by an increase in the levels of vimentin and decrease of E-cadherin in lung cancer A549 and 95D cells." (PMID 26919096, 2016).